NFE2L2 (NFE2 like bZIP transcription factor 2)
Diseases named in the same sentence as NFE2L2 in open-access papers (continued):
Sharing a sentence is not in itself a finding about the gene and the disease.
cervical cancer (12 papers, 2016 to 2024). A primary or metastatic malignant neoplasm involving the cervix. "Another study reported that miR-144 can inhibit the expression of NFE2L2, thereby reducing the proliferation and metastasis of cervical cancer cells." (PMID 34895046, 2021). "These pathways and the recurrently mutated genes involved therein, such as EP300, ARID1A, FBXW7, NFE2L2, PIK3CA, and ERBB2, were all found to be pathogenic in previous cervical cancer studies." (PMID 28390392, 2017). "Our understanding of PGRN-stimulated NFE2L2/ARE signaling not only characterizes the antioxidant role of PGRN under oxidative stress conditions but also provides new therapeutic interventions for PGRN in cervical cancer." (PMID 39695087, 2024). "Moreover, overexpression of NFE2L2 results in the abolishment of allicin-triggered cell apoptosis in cervical cancer cells, showing that the anti-tumor role of allicin is mainly increased by suppressing NFE2L2." (PMID 36497321, 2022). "One recent study of 228 cervical cancers using TCGA data identified SHKBP1, ERBB3, CASP8, HLA-A, and TGFBR2 as novel significantly mutated genes, and previously identified pathogenic genes including PIK3CA, EP300, ARID1A, and NFE2L2 were also confirmed." (PMID 28390392, 2017). "Furthermore, EP300, ARID1A, FBXW7, NFE2L2, PIK3CA, and ERBB2 have all been previously reported as pathogenic genes in cervical cancer, and we highlighted the roles of MLL2, MLL3, and CREBBP in the tumorigenesis." (PMID 28390392, 2017). "All these results suggest that the antioxidative effect of PGRN may depend on the NFE2L2/ARE signaling pathway activity and inhibiting NFE2L2 expression can suppress the antioxidative activity of PGRN in cervical cancer." (PMID 39695087, 2024).
steatosis (12 papers, 2016 to 2026). Increased lipid within the cytoplasm of cells. "In vitro experiments using HepG2 cells confirmed that miR-27a directly suppresses nuclear factor erythroid 2-related factor 2 (NFE2L2), and NFE2L2 overexpression counteracted miR-27a-induced mitochondrial damage and steatosis." (PMID 42197305, 2026). "Previous studies have shown that NFE2L2 can negatively regulate the expression of lipid synthesis genes and protect from steatosis." (PMID 38060313, 2023). "Studies have demonstrated that NFE2L2 knockout mice develop more severe steatosis and experience higher levels of oxidative stress than wild-type mice." (PMID 37822923, 2023). "The enhanced de novo lipogenesis was consistent with studies showing that NFE2L2 negatively regulates lipid synthesis genes in the liver and protects against steatosis." (PMID 38060313, 2023). "Furthermore, we observed that the steatosis-induced CKD mouse model showed the activation of Nfe2l2, an antioxidant transcription factor." (PMID 35294499, 2022). "Furthermore, we established NFE2L2 as a direct target of miR-34a-5p and demonstrated that GA inhibited lipid accumulation and ameliorated steatosis along with reducing miR-34a-5p expression in HepG2 cells." (PMID 35052597, 2021). "To test this, we isolated hepatocytes from control (Nox4fl/fl) and hepatocyte-specific NOX4-deficient mice (Alb-Cre Nox4fl/fl) fed a HFD for 10 weeks to induce steatosis and assessed H2O2 levels and the expression of NFE2L2 and its target genes." (PMID 38060313, 2023).
esophageal squamous cell carcinoma (11 papers, 2020 to 2026). Esophageal squamous cell carcinoma (ESCC) is a type of esophageal carcinoma (EC) that can affect any part of the esophagus, but is usually located in the upper or middle third. "A previous study shows that high expression of nuclear NFE2L2 predicts poor prognosis in patients with esophageal squamous cell carcinoma." (PMID 37794491, 2023).
gastric cancer (11 papers, 2015 to 2025). A primary or metastatic malignant neoplasm involving the stomach. "Another NFE2L2 variant, rs13001694, has been associated with an increased risk of developing myelodysplastic neoplasia and breast, colon, and stomach cancer." (PMID 40565143, 2025). "Results indicated that CXCR4 and NFE2L2 were the independent risk factor for the prognosis of gastric cancer (p < 0.05)." (PMID 38221932, 2024). "CXCR4 showed an up-regulated trend and NFE2L2 showed a down-regulated trend in stage I and stage II gastric cancer samples." (PMID 38221932, 2024). "Taken together, these findings further suggested the critical roles of CXCR4 and NFE2L2 in predicting the prognosis of stage I and stage II gastric cancer patients." (PMID 38221932, 2024). "CXCR4, SPP1, CXCL1, MMP9, and TIMP1 were up-regulated and NFE2L2 was down-regulated in gastric cancer cell lines compared with control." (PMID 38221932, 2024). "In conclusion, the present study identified two subtypes and a prognostic signature for stage I and stage II gastric cancer based on NRGs, such as CXCR4 and NFE2L2." (PMID 38221932, 2024).
Hepatic fibrosis (11 papers, 2013 to 2025). The presence of excessive fibrous connective tissue in the liver. "An in-vitro study showed that curcumin, through activation of NFE2L2, can promote lipocyte activation in stellate cells (HSCs) and repress hepatic fibrosis." (PMID 35405942, 2022).
leukemia (11 papers, 2014 to 2025). A malignant (clonal) hematologic disorder, involving hematopoietic stem cells and characterized by the presence of primitive or atypical myeloid or lymphoid cells in the bone marrow and the blood. "Compared to healthy BMMCs, we observed the TF networks of ZNF266, RORA, GTF3C2, ZNF76, ZNF383, IRF5 and NFE2L2 being top upregulated in all leukemia patients." (PMID 33408321, 2021). "Out of the 132 early‐specific TF‐binding sites, such as motifs for Bach1/2, Maf(k), and Nfe2l2, 109 (83%) were significantly enriched in leukemias, whereas of the 115 intermediate‐ and mature‐specific TFs only 12 (10%) were significantly enriched in T‐ALLs." (PMID 32755029, 2020). "Consistent with the present study, EANT enhanced the mRNA expressions of NFE2L2, CAT, TXN, HMOX1, and NQO1 genes in leukemia cells in response to EANT-induced oxidative stress." (PMID 34573042, 2021). "Future research should investigate whether targeting ferroptosis regulators, such as GPX4 and NFE2L2 (NRF2), could enhance the sensitivity of resistant leukemia cells to daunorubicin." (PMID 41360907, 2025). "The inducible expression of TXNDC12 during ferroptosis in leukemia cells is inhibited by the knockdown of the transcription factor ATF4, rather than NFE2L2." (PMID 38047088, 2023).
bladder cancer (10 papers, 2019 to 2025). "For example, mutations in KEAP1 and NFE2L2 have been reported in late-stage bladder cancer and NRF2 has been reported to be upregulated in a model of post-therapy recurrence of breast cancer." (PMID 33276631, 2020). "Choi once reported that bladder cancer with mutation of RB1 and NFE2L2 can be enriched into basal subtype of muscle-invasive bladder cancer, which could be divided into epithelial–basal and more clinically aggressive mesenchymal subtypes." (PMID 34122523, 2021). "Similarly, WFA upregulates the mRNA expression of antioxidant genes (NFE2L2, CAT, SOD1, TXN, GSR, NQO1, and HMOX1) in bladder cancer cells associated with oxidative stress generation." (PMID 34209212, 2021). "Mutations in NFE2L2 (Nrf2) are not frequently described as common in bladder cancer; however, analysis of TCGA data of activating mutations found in the Nrf2/pathway are common in carcinogen-exposed cancers (including bladder) and are associated with aggressive disease." (PMID 37175559, 2023).
endothelial dysfunction (10 papers, 2017 to 2024). In vascular diseases, endothelial dysfunction is a systemic pathological state of the endothelium (the inner lining of blood vessels) and can be broadly defined as an imbalance between vasodilating and vasoconstricting substances produced by (or acting on) the endothelium. "Interestingly, hydrogen sulfide (H2S) improves endothelial dysfunction by reducing the activation of NLRP3 inflammasome and oxidative stress in SHR, and after knocking down Nfe2l2, the protective effect of H2S was eliminated." (PMID 35204118, 2022). "Further, supplementation of miR‐200a inhibited aortic Keap1 expression, activated NRF2 signalling and attenuated hyperglycaemia‐induced oxidative stress, inflammation and endothelial dysfunction in the wild‐type, but not Nfe2l2 knockout, mice." (PMID 32628815, 2020).
esophageal cancer (10 papers, 2017 to 2023). A primary or metastatic malignant neoplasm involving the esophagus. "There were 301 NFE2L2 mutations (MUs, 3.0%) in the OrigiMed cohort with esophageal carcinoma (ESCA, 12.1%) ranking first followed by thyroid carcinoma (6.3%), gallbladder carcinoma (5.4%) and NSCLC (4.7%)." (PMID 37794491, 2023). "NFE2L2 is found mutated in tandem with other specific driver combinations not only in LUSC, but also in head-and-neck, bladder, and esophageal cancers." (PMID 35872531, 2022). "In patients with oesophageal cancer, metabolic reprogramming of the glutathione metabolism, as well as detoxification of ROS by activation of NFE2L2, enhances cancer progression, leading to poor clinical outcomes." (PMID 35281814, 2022). "NFE2L2 is a transcription factor that primarily affects the expression of antioxidant genes and its activation regulates a variety of cancer hallmarks related to EMT, including tumor aggressiveness, invasion, and metastasis formation, and has a significant impact in esophageal carcinoma (ESCA)." (PMID 36137089, 2022). "Similar to oesophageal cancer, the high levels of NRF2 activity found in CRC do not correlate with the presence of KEAP1 and NFE2L2 mutations, which are relatively rare according to analysis by the Cancer Genome Atlas Research Network of somatic mutations in CRC." (PMID 33276631, 2020).
head and neck squamous cell carcinoma (10 papers, 2015 to 2026). A squamous cell carcinoma that arises from any of the following anatomic sites: lip and oral cavity, nasal cavity, paranasal sinuses, pharynx, larynx, and salivary glands. "In NFE2L2‐mutated head and neck squamous cell carcinoma, CSF3 recruits MDSCs to mediate chemotherapy resistance." (PMID 37666495, 2024). "However, the mechanism underlying the hotspot NFE2L2-79 (HR = 3.8, p = 0.003) observed in HNSC (head and neck squamous cell carcinoma) remains poorly understood." (PMID 38473427, 2024). "Indeed, EGF expression correlated with NRF2 activation in different cancer types, as we showed for NFE2L2/KEAP1 mutant lung adenocarcinoma as well as head and neck squamous cell carcinoma." (PMID 33916908, 2021).
Hypertension (10 papers, 2016 to 2024). The presence of chronic increased pressure in the systemic arterial system. "This polymorphism of NFE2L2 has also been implicated in other diseases, such as Parkinson’s disease (PD), hypertension, and cardiovascular disease." (PMID 31340446, 2019). "In hypertension, the decreased transcriptional activity of nuclear factor erythroid 2-related factor 2 (Nrf2 or Nfe2l2) correlates with heightened oxidative stress in APCs and impaired control of various antioxidant genes." (PMID 38791545, 2024).
liver cancer (10 papers, 2013 to 2024). An epithelial or non-epithelial malignant neoplasm that arises from the liver. "Genes associated with oxidative stress are altered, such as activating mutations in NFE2L2 (encoding NRF2) or inactivating KEAP1 mutations in 5–15% of liver cancer cases." (PMID 35158835, 2022). "Cadmium stress induces liver cancer cell death by upregulating miR-365a-3p and downregulating its target NFE2L2." (PMID 38892270, 2024). "Somatic mutations that impair the function of KEAP1 and lead to the constitutive stabilisation of NFE2L2 have been found in lung, gallbladder and liver cancer in humans." (PMID 23724128, 2013). "The upregulation of NFE2L2 inhibits the ferroptosis of liver cancer cells." (PMID 38892270, 2024). "On the other hand, an extract from graviola leaves—rich in kaempferol-rutinoside—increased the expression of the NFE2L2 gene in HepG2 liver cancer cells but did not affect the expression of the HO-1 gene." (PMID 35056649, 2022).
multiple sclerosis (10 papers, 2016 to 2024). A progressive autoimmune disorder affecting the central nervous system resulting in demyelination. "Nfe2l2 upregulation was similar between astrocytes from GFAP-Nrf2 mice (fold change 2.3 versus wildtype control) and multiple sclerosis astrocytes (fold change 1.8 versus healthy control) (IPA Analysis Match19,29), indicating a disease-relevant modulation of astrocytic Nrf2 activation in the mice." (PMID 37291151, 2023).
neuroblastoma (10 papers, 2013 to 2025). Neuroblastoma (NB) is the most common solid, extracranial childhood tumor. "Although there is no direct proof of chromatin structure alterations in either NFE2L2 or KEAP-1 in neuroblastoma, there are a few studies supporting potential epigenetic modifications of both genes." (PMID 38666930, 2024). "The mechanism behind this phenomenon is that in human neuroblastoma cells, it inactivates NFE2L2 and opposes the anti-inflammatory and antineoplastic effects of a natural drug, schisandrin B." (PMID 36768958, 2023). "Initial experiments were carried out in SK-N-BE dopaminergic neuroblastoma cells stably transfected with the bioluminescent NFE2L2 activity reporter pARE-luc2-ires-tdTomato, named SK-ARE-luc2." (PMID 34551802, 2021). "In human neuroblastoma cells, it was reported that the upregulations of miR-142, miR-144, and miR-153 could decrease NFE2L2 expression by targeting its 3′-UTR." (PMID 36768958, 2023). "Subsequently, Mahimainathan’s group identified and validated for the first time a series of miRNAs, miR-153, miR27a, miR142-5p, and also miR-144 in neuronal cells, specifically in human SH-SY5Y neuroblastoma cells, which directly mediate repression of NFE2L2 in a KEAP1-independent manner." (PMID 34663413, 2021). "Upregulated expression of antioxidant genes, viz., HMOX1, NFE2l2, SLC7A11, and NADPH oxidase, and downregulated expression of monooxygenase enzymes in our study could be a putative approach to deal with the oxidative stress in WS-treated human neuroblastoma SK-N-SH cells." (PMID 40636521, 2025).
pulmonary fibrosis (10 papers, 2012 to 2025). Chronic progressive interstitial lung disorder characterized by the replacement of the lung tissue by connective tissue, leading to progressive dyspnea, respiratory failure, or right heart failure. "Liproxstatin-1-mediated NFE2L2 activation prevents radiation-induced pulmonary fibrosis, suggesting a protective role for NFE2L2 in limiting lung fibrosis." (PMID 33268902, 2021). "Besides, sodium Tanshinone IIA sulfonate, an extract of Salvia miltiorrhiza (Danshen) increases the nuclear expression of nuclear factor, erythroid 2-like 2 (NFE2L2) to attenuate pulmonary fibrosis." (PMID 35832651, 2022). "NFE2L2 (NF-E2–related transcription factor 2, also called NRF2) stimulation increases the expression of KLF9 (Kruppel-like factor 9), resulting in increases in ROS production and subsequent cell death, however they show diverse functions in bleomycin-induced pulmonary fibrosis in mice and IPF." (PMID 35980387, 2022).
viral infection (9 papers, 2017 to 2025). "If these drugs inhibited hCoV-229E infection by activation of NFE2L2 signaling, a knock-out of NFE2L2 would be expected to promote viral infection." (PMID 38319076, 2024). "In particular, the NFE2L2/NRF2 pathway is involved in the control of the innate immune response, cytosolic DNA sensing in viral infection, and survival in sepsis." (PMID 35454818, 2022). "An example of such a novel regulator was NFE2L2, which controls the activity of HMOX1 in the context of viral infection." (PMID 34664389, 2021). "In addition, we provide evidence that NFE2L2/KEAP1, FDFT1, and AHR are potentially druggable host targets with relevance for various viral infections." (PMID 38319076, 2024).
acute myeloid leukemia (8 papers, 2020 to 2025). Acute myeloid leukemia (AML) is a group of neoplasms arising from precursor cells committed to the myeloid cell-line differentiation. "NFE2L2 is constitutively active in human acute myeloid leukemia (AML) cells, and these cells possess greater constitutive nuclear levels of NFE2L2 than normal control CD34+ cells." (PMID 35056649, 2022). "Constitutive NF-κB activation mediates upregulation of NFE2L2 gene and contributes to high basal NRF2 activity that renders resistance to chemotherapy in acute myeloid leukemia (AML)." (PMID 32640524, 2020).
liver diseases (8 papers, 2019 to 2024). "Together, these results suggest that the presence of the nucleotide A in the position -178 of the promoter region of NFE2L2 is associated with cirrhotic liver disease, since both ALD and HCV samples preferentially showed this polymorphism." (PMID 31340446, 2019). "The liver tissues of Sofosbuvir-exposed female rats showed induced NF-κB expression, high MDA and 8-OHdG contents, and suppressed Nfe2l2 expression, which might indicate a state of inflammation and oxidative stress that could contribute to the development and progression of liver diseases." (PMID 37958828, 2023).
acute kidney injury (7 papers, 2012 to 2026). Sudden and sustained deterioration of the kidney function characterized by decreased glomerular filtration rate, increased serum creatinine or oliguria. "The nuclear factor erythroid 2-related factor 2 (NFE2L2/NRF2)—antioxidant responsive element (ARE) prevents the progression of acute kidney injury (AKI) to CKD by regulating cellular antioxidant defenses." (PMID 34680074, 2021).
amyotrophic lateral sclerosis (7 papers, 2009 to 2023). Amyotrophic lateral sclerosis (ALS) is a neurodegenerative disease characterized by progressive muscular paralysis reflecting degeneration of motor neurons in the primary motor cortex, corticospinal tracts, brainstem and spinal cord. "In amyotrophic lateral sclerosis, hnRNPK binds to antioxidant NFE2L2 (NFE2-like BZIP transcription factor 2) and GPX1 (glutathione peroxidase 1) transcripts." (PMID 36735291, 2023).